PDE11A (phosphodiesterase 11A)
Description:
Plays a role in signal transduction by regulating the intracellular concentration of cyclic nucleotides cAMP and cGMP. Catalyzes the hydrolysis of both cAMP and cGMP to 5'-AMP and 5'-GMP, respectively.
Synonyms: PPNAD2
Tractability: Small molecule: a high-quality ligand is known; it belongs to a druggable protein family. PROTAC: a small molecule that binds it is known.
Target class: Phosphodiesterase; Phosphodiesterase 11; Enzyme; Phosphodiesterase 11A
Gene: Protein-coding gene on chromosome 2 (177,623,244 to 178,108,339, reverse strand). Ensembl gene ENSG00000128655.
Subcellular location: Cytoplasm, cytosol
Subcellular location (Human Protein Atlas): Microtubules; Primary cilium; Basal body; Centriolar satellite; Cytokinetic bridge; Cytosol; Mitotic spindle; Nucleoplasm
Pathways (Reactome):
Hemostasis: cGMP effects
Signal Transduction: G alpha (s) signalling events
Gene Ontology:
Molecular function: 3',5'-cGMP-stimulated cyclic-nucleotide phosphodiesterase activity; 3',5'-cyclic-AMP phosphodiesterase activity; 3',5'-cyclic-GMP phosphodiesterase activity; cGMP binding; 3',5'-cyclic-nucleotide phosphodiesterase activity; cyclic-nucleotide phosphodiesterase activity; phosphoric diester hydrolase activity
Biological process: negative regulation of cAMP/PKA signal transduction; negative regulation of receptor guanylyl cyclase signaling pathway; signal transduction
Cellular component: cytosol
Genetic constraint (gnomAD): Loss-of-function variants: 27 observed, 33.3 expected, observed/expected ratio (o/e) 0.81, 90% interval 0.6 to 1.12. The upper end of that interval is the gene's LOEUF score, 1.12, which puts it in group 4 of 6, group 1 being the genes least tolerant of losing a copy. Missense variants: 601 observed, 619.96 expected, observed/expected ratio (o/e) 0.97, 90% interval 0.91 to 1.04. Synonymous variants: 206 observed, 242.66 expected, observed/expected ratio (o/e) 0.85, 90% interval 0.76 to 0.95.
Homologues: Orthologues: macaque PDE11A (98% identical), chimpanzee PDE11A (97% identical), pig PDE11A (96% identical), mouse Pde11a (95% identical), rat Cyct (94% identical), dog PDE11A (91% identical), guinea pig PDE11A (91% identical), zebrafish pde11al (71% identical), Drosophila melanogaster Pde11 (43% identical), Drosophila melanogaster Pde8 (15% identical), Drosophila melanogaster Pde9 (12% identical), Caenorhabditis elegans pde-6 (12% identical), and 2 more. Paralogues in human: PDE5A (38% identical), PDE6B (28% identical), PDE6C (28% identical), PDE6A (27% identical), PDE2A (27% identical), PDE10A (25% identical), PDE8A (17% identical), PDE8B (17% identical), PDE3A (17% identical), PDE4D (16% identical), PDE4A (15% identical), PDE4B (15% identical), and 8 more.
Diseases named in the same sentence as PDE11A in open-access papers:
PDE11A is named in the same sentence as 55 diseases in open-access papers, as found by Europe PMC text mining. Sharing a sentence is not in itself a finding about the gene and the disease. The quoted sentences say what the papers report.
Cushing syndrome (8 papers, 2015 to 2026). Cushing's syndrome (CS) encompasses a group of hormonal disorders caused by prolonged and high exposure levels to glucocorticoids that can be of either endogenous (adrenal cortex production) or exogenous (iatrogenic) origin. "Inactivating mutations in PDE11A cause isolated macronodular adrenal hyperplasia and Cushing syndrome that is characterized by central obesity and a panel of metabolic sequelae, confirming a role for this gene in metabolic regulation and energy balance." (PMID 38027204, 2023). "Sporadic cases of micronodular adrenal hyperplasia causing ACTH-independent Cushing syndrome were also linked to mutations in phosphodiesterase-11A (PDE11A) and phosphodiesterase 8B (PDE8B)." (PMID 25775093, 2015). "Mutations in PRKAR1A, PDE11A, and PDE8B have all been implicated in the pathogenesis of bilateral micronodular adrenocortical disease presenting with Cushing syndrome." (PMID 29594118, 2018). "Benign adrenal cortical tumors presenting with Cushing syndrome often have diverse mutations (PRKACA, PRKAR1A, GNAS, PDE11A, and PDE8B) involving the cyclic AMP signaling pathway." (PMID 29594118, 2018). "Germline PDE11A variant mutation has also been described with adrenal enlargement but without evidence of Cushing syndrome." (PMID 29594118, 2018).
adrenal hyperplasia (6 papers, 2015 to 2023). "This interaction is more commonly seen in Carney Complex patients with adrenal hyperplasia, in that patients with adrenal hyperplasia (i.e., primary pigmented nodular adrenocortical disease) were significantly more frequently carriers of PDE11A variants than those without adrenal hyperplasia." (PMID 36313756, 2022). "Interference of cAMP/cGMP signaling pathway has been shown to be linked to tumorigenesis and PDEs overexpression has been already described in several cancer types such happened for PDE11A and PDE8B, in adrenal hyperplasia/adenomas." (PMID 37108780, 2023).
testicular germ cell tumor (5 papers, 2016 to 2024). A germ cell tumor arising from the testis. "Rare germline alterations in PDE11A have been associated with prostate and testicular germ cell tumor susceptibility." (PMID 31921681, 2019). "In one patient we found a frameshift pathogenic variant p.G57fs in PDE11A, a gene previously associated with different neoplasms including Carney multiple neoplasia complex, prostate cancer and testicular germ cell tumors." (PMID 30262796, 2018). "In addition, downregulation of PDE11A expression and inactivating variants of the gene have been found in hereditary and sporadic testicular germ cell tumors, as well as in prostatic cancer." (PMID 27625633, 2016). "PDE11A has been identified as another genetic modifying factor for the development of testicular tumors and it has been reported that PDE11A-inactivating variants may increase the risk of developing familial and bilateral testicular germ cell tumor." (PMID 37108780, 2023). "The PDE11A gene encodes the PDE protein superfamily member and is associated with testicular germ cell tumors (TGCTs)." (PMID 38540412, 2024).
adenoma (4 papers, 2016 to 2023). A neoplasm arising from the epithelium. "Thereafter, PDE11A or PDE8B genetic variants have been found in other ACTs, including macronodular adrenocortical hyperplasias and cortisol-producing adenomas." (PMID 27625633, 2016).
adrenocortical adenoma (4 papers, 2018 to 2022). "Many humans with germline PDE11A mutations will also develop cortisol-secreting adrenal adenomas." (PMID 36313756, 2022). "There are also some intriguing genetic interactions between PRKAR1A and PDE11A in the pathogenesis of adrenal cortical adenomas." (PMID 36313756, 2022). "Alterations of PDE11A and PDE8B were not specific of PPNAD and were further described in other types of adrenocortical tumors: PBMAH, adrenocortical adenomas (ACAs), nonsecreting adrenocortical adenoma and adrenocortical carcinomas (ACCs)." (PMID 32783015, 2020).
adrenocortical tumors (4 papers, 2018 to 2022). "It is worth noting that variants in PDE11A and PDE8B have been found in other types of adrenocortical tumors as well." (PMID 36105398, 2022). "However, genetic alterations in PDE11A and PDE8B have also been described in other kinds of adrenocortical tumors." (PMID 35625779, 2022). "Furthermore, in a cohort of patients with adrenocortical tumors without variants in PRKAR1A, GNAS, or PDE11A, 7 patients harbored variants in PDE8B." (PMID 36105398, 2022). "Furthermore, in a study of samples from 27 patients with adrenocortical tumors without mutations in GNAS, PRKAR1A, PDE11A, or PDE8B, abnormalities of the cAMP-signaling pathway were found, with mutation-negative ACAs having significantly decreased PDE activity." (PMID 30456751, 2018).
Carney complex (4 papers, 2018 to 2025). Carney complex (CNC) is characterized by spotty skin pigmentation, endocrine overactivity and myxomas. "This phenotypic effect of loss-of-function PDE11A mutations is observed in patients with Carney Complex and PRKAR1A mutations who develop Sertoli cell tumors, as described in more detail below." (PMID 36313756, 2022). "A significant proportion of patients with Carney Complex with PRKAR1A mutations also have germline loss-of-function mutations in PDE11A." (PMID 36313756, 2022). "In addition to their PRKAR1A mutation, LCCSCT patients with Carney Complex have an increased frequency of germline loss-of-function mutations in PDE11A." (PMID 36313756, 2022). "Furthermore, a high frequency of PDE11A variants has been identified in patients with Carney complex (CNC), especially in those with PRKAR1A mutations." (PMID 41179677, 2025). "However, clinically there are differences between patients with Carney Complex and PDE11A mutation carriers, as the extra-adrenal features typical of Carney Complex are usually not present in PDE11A carriers." (PMID 36313756, 2022).
Obesity (4 papers, 2018 to 2025). Accumulation of substantial excess body fat. "The results revealed that 18 of the DMR genes were associated with addiction and obesity (ADCY3; ADCY9; ATF4; CDK5R1; CHRNB2; GABRD; GABRG3; GNB1; GNB3; GRK5; HDAC4; HDAC9; MAP2K1; PDE11A; PDE2A; PDE3A; PPP1CA; SLC6A3)." (PMID 34389046, 2021). "Then, we selected 5 variants in genes previously reported to be associated with obesity, adipogenesis or linked to obesity-associated traits by genome-wide association studies (SLC25A5, AIM2, SNX16, CAMKK2 and PDE11A) for further analysis to identify candidate MOVs." (PMID 38469147, 2024).
adrenal tumors (3 papers, 2020 to 2024). "Collectively, these murine models produce additional support for the functional significance of PRKAR1A and PDE11A mutations in the development of adrenal tumors and that their gene products act in a common pathway." (PMID 36313756, 2022). "Therefore, PDE11A mutation might indicate the occurrence of PPNAD and other types of adrenal tumors." (PMID 39006359, 2024). "As a genetic modifying factor for the development of testicular and adrenal tumors in patients with germline PRKAR1A mutation, PDE11A is probably a phenotype modifying gene but not a causative gene." (PMID 39006359, 2024).
asthma (3 papers, 2012 to 2023). "PDE11A defects have been linked to several cancers (adrenal, testicular, and prostate) and to major depression, bipolar disorder, and asthma, implicating specific PDE11A inhibitors as potential drug targets." (PMID 38027204, 2023). "In addition, we genotyped four SNPs that have been reported to be associated with asthma, rs7216389 in ORMDL3, rs11684634 in PDE11A, rs1544791 in PDE4D and rs2706347 in RAD50." (PMID 23046476, 2012).
McCune-Albright syndrome (3 papers, 2018 to 2026). McCune-Albright syndrome (MAS) is classically defined by the clinical triad of fibrous dysplasia of bone (FD), cafe-au-lait skin spots, and precocious puberty (PP). "In addition to postzygotic somatic mosaicism of GNAS in McCune-Albright syndrome, rare examples of hereditary PBMAH have been described in the setting of APC-, MEN1-, FH-, PDE8B-, and PDE11A variant-driven pathogenesis." (PMID 29594118, 2018). "PBMAH may also result from alterations in MC2R, PRKACA, and phosphodiesterase (PDE)11A genes, and it can occur as part of familial tumor syndromes such as McCune-Albright syndrome (GNAS), MEN1, familial APC, or hereditary leiomyomatosis and renal cell carcinoma (FH gene variant)." (PMID 41503047, 2026).
Sertoli cell tumor (3 papers, 2022 to 2023). A sex cord-stromal tumor of the testis or the ovary. "In addition, targeted sequencing of PDE11A revealed that patients with CNC that also had PPNAD and/or testicular large cell calcifying Sertoli cell tumors were more likely to have variants in PDE11A, compared to patients without these tumors." (PMID 36105398, 2022).
testicular tumors (3 papers, 2021 to 2023). "Interestingly, two recent studies investigated the putative link between testicular tumours and PDE11A polymorphisms (SNPs), finding that inactivating PDE11A variants seem to be associated with TGCT risk in both familial and sporadic cases." (PMID 33661511, 2021). "Moreover, we identified ten new PDE11A polymorphisms, two of which significantly associated with a lower risk of testicular tumour." (PMID 33661511, 2021). "Analysis of associations between testicular cancer and PDE11A polymorphisms revealed that the homozygote AA, in the case of G223A, and the heterozygote AG, in the case of A288G, were significantly associated with a lower risk of testicular tumour than the other genotypes." (PMID 33661511, 2021).
adrenal Cushing syndrome (2 papers, 2018 to 2020). "Genome-wide associations studies demonstrate that PDE2A, PDE8B, and PDE11A modulate steroidogenesis and are associated with adrenal Cushing’s syndrome and/or bilateral adrenal hyperplasia." (PMID 32098292, 2020). "Germline or sporadic inactivating PRKAR1A, PDE11A, and PDE8B mutations have also been described in i-PPNAD causing adrenal Cushing syndrome." (PMID 29594118, 2018).
age (2 papers, 2022 to 2025). A temporal measurement of the time period elapsed since an identifiable point in the life cycle of an organism. "Age-related increases in PDE11A expression occur in human and rodent hippocampus and cause age-related cognitive decline of social memories." (PMID 40558524, 2025). "It will be of interest to future studies to determine if the ability of PDE11A deletion to prevent age‐related cognitive decline of social aLTMs is a direct consequence of ameliorating age‐related deficits in circadian rhythms and/or quality of sleep." (PMID 36073342, 2022).
Alzheimer disease (2 papers, 2022 to 2025). A progressive, neurodegenerative disease characterized by loss of function and death of nerve cells in several areas of the brain leading to loss of cognitive function such as memory and language. "Together, our findings complement those of Qin and colleagues who associated rare PDE11A mutations with early‐onset Alzheimer's Disease." (PMID 36073342, 2022). "In this context, it may be interesting to note that two rare PDE11A variants have been associated with early-onset Alzheimer’s disease and exacerbated age-related increases in PDE11A expression have been associated with dementia in elderly traumatic brain injury patients." (PMID 40558524, 2025). "This is particularly interesting given that pathway analysis of our previous proteomics study of VHIPP from Pde11a KO versus WT mice, along with pathway analyses of the RNA sequencing and phosphoproteomics studies reported herein, identified the Alzheimer's disease pathway." (PMID 36073342, 2022). "Notably, mRNA expression and phosphoproteomic changes in VHIPP of old Pde11a WT vs KO mice were enriched for pathways related to Alzheimer's disease, axon guidance, regulation of transport, chemical synaptic transmission, as well as the axon, synapse, presynapse, and synaptic vesicle." (PMID 36073342, 2022). "In elderly humans with a history of TBI, hippocampal PDE11A mRNA expression is significantly higher in those that developed Alzheimer's disease or a related dementia versus those that did not." (PMID 36073342, 2022).
amnesia (2 papers, 2021 to 2022). Pathologic partial or complete loss of the ability to recall past experiences ( AMNESIA, RETROGRADE) or to form new memories ( AMNESIA, ANTEROGRADE). "The effect of PDE11A deletion on social memory in young adult mice is quite unique in that it triggers a transient amnesia that ultimately produces a stronger remote long‐term memory (LTM; i.e., intact short‐term memory, impaired recent LTM, improved remote LTM)." (PMID 36073342, 2022). "For example, Pde11a KO mice demonstrate a transient amnesia for social memories, with normal short-term memory, no recent long-term memory, and spontaneously improved remote LTM relative to WT littermates." (PMID 34887755, 2021).
cognitive decline (2 papers, 2022 to 2025). "Together, these results suggest that increases in PDE11A expression that occur with age and TBI‐associated dementia contribute to cognitive decline." (PMID 36073342, 2022).
dementia (2 papers, 2022 to 2025). Loss of intellectual abilities interfering with an individual's social and occupational functions. "The fact that age‐related increases in PDE11A are exacerbated in elderly patients with TBI‐associated dementia is consistent with reports in humans that TBI worsens age‐related decreases in hippocampal cAMP levels as well as ARCD." (PMID 36073342, 2022). "The TBI‐associated dementia‐related increase in PDE expression is unique to PDE11A in that PDE2A, PDE5A, and PDE10A expression remained unchanged." (PMID 36073342, 2022). "Here, we found that both aging and traumatic brain injury‐associated dementia increased the expression of the cAMP/cGMP‐degrading enzyme phosphodiesterase 11A (PDE11A) in the human hippocampus." (PMID 36073342, 2022). "Together, these data suggest that PDE11A expression uniquely increases with age in the human hippocampus in part due to increases in transcript stability, and that these age‐related increases can be exacerbated in those with dementia and a history of TBI." (PMID 36073342, 2022). "Among elderly humans with a history of TBI, hippocampal PDE11A mRNA expression was significantly higher in those that developed dementia versus those that did not." (PMID 36073342, 2022). "Pathway analyses from an RNA sequencing and confirmatory phosphoproteomics study comparing VHIPP from old Pde11a WT vs KO mice identified multiple mechanisms by which PDE11A4 may contribute to ARCD and/or dementia." (PMID 36073342, 2022).
extrapulmonary tuberculosis (2 papers, 2011 to 2012). A tuberculosis that occurs at body sites other than the lung. "Recent reports elsewhere identified that single nucleotide polymorphisms rs4893980 on gene PDE11A of chromosome number 2, rs10488286 on gene KCND2 of chromosome number 7 and rs2026414 on gene PCDH15 of chromosome number 10 in humans were associated with extrapulmonary tuberculosis." (PMID 22770435, 2012).
myopia (2 papers, 2023 to 2025). "Recently, a Y727C variant in the dual-specific 3′,5′-cyclic nucleotide phosphodiesterase 11A (PDE11A-Y727C) was linked to increased sleep quality and reduced myopia risk in humans." (PMID 38132157, 2023). "Of particular interest to the fact that PDE11A-Y727C is both protective against myopia and enhancing to sleep quality, myopia has been associated with reduced sleep quality and a dysregulated retinal circadian clock." (PMID 38132157, 2023). "It is quite possible that in the context of a disease-like state (e.g., a genetic mouse model with increased susceptibility to myopia, a model of sleep deprivation, etc.), Pde11a deletion would provide a protective action." (PMID 38132157, 2023). "Interestingly, a Y727C missense mutation in PDE11A has been genetically linked in humans to improved sleep quality and a reduced risk of myopia." (PMID 38132157, 2023). "At PDE11A, the missense variant rs17400325 (Y727C, P-REECAP < 3×10−9) colocalized with myopia in FinnGen (PP-H4 = 0.999) despite not reaching genome-wide significance there." (PMID 41332846, 2025).
refractive error (2 papers, 2014 to 2025). A defect in the focusing of light on the retina as in astigmatism, myopia, or hyperopia. "Rare-variant analyses have previously implicated PDE11A in refractive error and myopia, and conditional image generation linked the risk allele to a brighter fundus and foveal greying, consistent with choroidal thinning in myopic remodeling." (PMID 41332846, 2025).